PRKCG (protein kinase C gamma)
Description:
Calcium-activated, phospholipid- and diacylglycerol (DAG)- dependent serine/threonine-protein kinase that plays diverse roles in neuronal cells and eye tissues, such as regulation of the neuronal receptors GRIA4/GLUR4 and GRIN1/NMDAR1, modulation of receptors and neuronal functions related to sensitivity to opiates, pain and alcohol, mediation of synaptic function and cell survival after ischemia, and inhibition of gap junction activity after oxidative stress. Binds and phosphorylates GRIA4/GLUR4 glutamate receptor and regulates its function by increasing plasma membrane-associated GRIA4 expression. In primary cerebellar neurons treated with the agonist 3,5-dihyidroxyphenylglycine, functions downstream of the metabotropic glutamate receptor GRM5/MGLUR5 and phosphorylates GRIN1/NMDAR1 receptor which plays a key role in synaptic plasticity, synaptogenesis, excitotoxicity, memory acquisition and learning. May be involved in the regulation of hippocampal long-term potentiation (LTP), but may be not necessary for the process of synaptic plasticity. May be involved in desensitization of mu-type opioid receptor-mediated G protein activation in the spinal cord, and may be critical for the development and/or maintenance of morphine-induced reinforcing effects in the limbic forebrain. May modulate the functionality of mu-type-opioid receptors by participating in a signaling pathway which leads to the phosphorylation and degradation of opioid receptors. May also contributes to chronic morphine-induced changes in nociceptive processing. Plays a role in neuropathic pain mechanisms and contributes to the maintenance of the allodynia pain produced by peripheral inflammation. Plays an important role in initial sensitivity and tolerance to ethanol, by mediating the behavioral effects of ethanol as well as the effects of this drug on the GABA(A) receptors. During and after cerebral ischemia modulate neurotransmission and cell survival in synaptic membranes, and is involved in insulin-induced inhibition of necrosis, an important mechanism for minimizing ischemic injury. Required for the elimination of multiple climbing fibers during innervation of Purkinje cells in developing cerebellum. Is activated in lens epithelial cells upon hydrogen peroxide treatment, and phosphorylates connexin-43 (GJA1/CX43), resulting in disassembly of GJA1 gap junction plaques and inhibition of gap junction activity which could provide a protective effect against oxidative stress (By similarity). Involved in the phase resetting of the cerebral cortex circadian clock during temporally restricted feeding. Stabilizes the core clock component BMAL1 by interfering with its ubiquitination, thus suppressing its degradation, resulting in phase resetting of the cerebral cortex clock (By similarity). Phosphorylates and activates LRRK1, which phosphorylates RAB proteins involved in intracellular trafficking.
Synonyms: PKC-gamma; PKCG; PKCC; MGC57564; PKCγ; PKCI(3); PKCgamma; SCA14
Tractability: Small molecule: an approved drug acts on it; a high-quality ligand is known; it belongs to a druggable protein family. Antibody: UniProt places it where antibodies can reach, with high confidence; its Gene Ontology location is reachable by antibodies, with medium confidence. PROTAC: UniProt records ubiquitination sites on it; ubiquitination databases record sites on it; its protein half-life has been measured; a small molecule that binds it is known.
Target class: AGC protein kinase PKC family; AGC protein kinase PKC alpha subfamily; Enzyme; Kinase; AGC protein kinase group; Protein Kinase
Gene: Protein-coding gene on chromosome 19 (53,879,190 to 53,907,652, forward strand). Ensembl gene ENSG00000126583.
Subcellular location: Cytoplasm; Cytoplasm, perinuclear region; Cell membrane; Synapse, synaptosome; Cell projection, dendrite
Pathways (Reactome):
Signal Transduction: Calmodulin induced events; G alpha (z) signalling events; WNT5A-dependent internalization of FZD4
Hemostasis: Disinhibition of SNARE formation; Response to elevated platelet cytosolic Ca2+
Neuronal System: Trafficking of GluR2-containing AMPA receptors
Gene Ontology:
Molecular function: calcium,diacylglycerol-dependent serine/threonine kinase activity; protein binding; protein kinase activity; protein serine/threonine/tyrosine kinase activity; diacylglycerol-dependent serine/threonine kinase activity; protein serine/threonine kinase activity; ATP binding; protein serine kinase activity; zinc ion binding
Biological process: negative regulation of protein catabolic process; negative regulation of protein ubiquitination; phospholipase C-activating G protein-coupled receptor signaling pathway; positive regulation of mismatch repair; intracellular signal transduction; negative regulation of neuron apoptotic process; negative regulation of proteasomal protein catabolic process; regulation of circadian rhythm; regulation of response to food; response to morphine; response to pain; chemical synaptic transmission; innervation; learning or memory; long-term synaptic potentiation; regulation of synaptic vesicle exocytosis; response to angiotensin; response to psychosocial stress; response to toxic substance
Cellular component: plasma membrane; cytosol; dendrite; perinuclear region of cytoplasm; postsynaptic cytosol; calyx of Held; cell-cell junction; cytoplasm; nucleus; postsynapse; postsynaptic density; presynaptic cytosol; synapse; synaptic membrane
Genetic constraint (gnomAD): Loss-of-function variants: 28 observed, 80.58 expected, observed/expected ratio (o/e) 0.35, 90% interval 0.26 to 0.48. The upper end of that interval is the gene's LOEUF score, 0.48, which puts it in group 2 of 6, group 1 being the genes least tolerant of losing a copy. Missense variants: 611 observed, 932.01 expected, observed/expected ratio (o/e) 0.66, 90% interval 0.61 to 0.7. Synonymous variants: 366 observed, 370.79 expected, observed/expected ratio (o/e) 0.99, 90% interval 0.9 to 1.08.
Homologues: Orthologues: chimpanzee PRKCG (99% identical), macaque PRKCG (99% identical), mouse Prkcg (99% identical), rat Prkcg (99% identical), dog PRKCG (99% identical), guinea pig PRKCG (98% identical), pig PRKCG (97% identical), tropical clawed frog prkcg (81% identical), rabbit PRKCG (80% identical), zebrafish prkcg (64% identical), Drosophila melanogaster Pkc53E (61% identical), Caenorhabditis elegans pkc-2 (61% identical), and 5 more. Paralogues in human: PRKCA (69% identical), PRKCB (68% identical), PRKCE (34% identical), PRKCH (33% identical), PKN2 (33% identical), PKN1 (32% identical), PKN3 (29% identical), PRKCI (29% identical), PRKCZ (29% identical).
Diseases named in the same sentence as PRKCG in open-access papers:
PRKCG is named in the same sentence as 110 diseases in open-access papers, as found by Europe PMC text mining. Sharing a sentence is not in itself a finding about the gene and the disease. The quoted sentences say what the papers report.
Ataxia (35 papers, 2014 to 2026). Ataxia refers to impaired coordination of voluntary muscle movement. "We describe the genomic analysis of this family of Argentinian descent in which three affected siblings presenting with spinocerebellar ataxia were found to have spinocerebellar ataxia type 14 (SCA14) due to mutation of the protein kinase C gamma (PRKCG) gene." (PMID 37101238, 2023). "PRKCG, a gene known to cause a rare form of ataxia (SCA14), was also found to be common, as was SPG7, which had a similar high frequency." (PMID 34445196, 2021). "The disease usually manifests with ataxia, but previous reports suggested PRKCG variants in retinal pathology." (PMID 32338350, 2020). "In our laboratory, we are interested in the role of protein kinase C gamma (PKCγ) for Purkinje cell dendritic development and for the pathogenesis of spinocerebellar ataxias (SCAs)." (PMID 34536317, 2021). "Finally, we describe one patient, who suffered from ataxia but carried a VUS in the catalytic domain of PRKCG (R634H)." (PMID 32338350, 2020).
spinocerebellar ataxia type 14 (26 papers, 2008 to 2026). Spinocerebellar ataxia type 14 (SCA14) is a rare mild subtype of type I autosomal dominant cerebellar ataxia (ADCA type I). "Whole exome sequencing was performed on three affected and two unaffected family members and revealed a dominant pathogenic variant, p.Gln127Arg (19:54392986 A>G), in the protein kinase C gamma gene, and the family was diagnosed with spinocerebellar ataxia type 14." (PMID 37101238, 2023). "Interestingly, mutations in the PRKCG gene coding for PKCγ are associated with Purkinje cells loss and impaired motor functions in spinocerebellar ataxia 14 (SCA14)." (PMID 32860158, 2020). "While dominant Spinocerebellar Ataxia Type 14 (SCA14) is typically associated with missense mutations in PRKCG, truncating variants have been reported in homozygous or compound heterozygous states in patients with a recessive phenotype." (PMID 41002930, 2025). "Spinocerebellar ataxia type 14 (SCA14) is a rare variant of SCAs caused by missense mutations or deletions in the PRKCG gene encoding the protein kinase C γ (PKCγ)." (PMID 36011327, 2022). "Within SCAs, spinocerebellar ataxia type 14 (SCA14) (OMIM 605361) is an autosomal dominant neurodegenerative disease caused by mutations in the PRKCG gene encoding the protein kinase C γ (PKCγ) protein." (PMID 36011327, 2022). "Specifically, point mutations identified in the PRKCG gene, which encodes for the conventional protein kinase C γ (PKCγ), are responsible for causing spinocerebellar ataxia type 14 (SCA14)." (PMID 34737895, 2021). "Spinocerebellar ataxia type 14 (SCA14) is a rare autosomal dominant neurodegenerative disease caused by mutations in protein kinase C gamma gene (PRKCG), encoding the PKCγ protein, leading to a progressive cerebellar atrophy and dysfunction characterized by motor impairments and cognitive decline." (PMID 41288860, 2025). "Among these, spinocerebellar ataxia type 14 (SCA14) stems from missense mutations or deletions within the PRKCG gene, encoding protein kinase C gamma (PKCγ), a pivotal signaling molecule abundant in Purkinje cells." (PMID 40332155, 2025). "In this viewpoint article we will initially focus on one particular subtype, spinocerebellar ataxia type 14 (SCA14), which is caused by mutations in the gene of Protein Kinase C gamma (PKCγ) and we will discuss how the mutations might cause the disease." (PMID 37426070, 2023). "Spinocerebellar ataxia 14 (SCA14; OMIM 605361) is a rare autosomal dominant neurodegenerative disease caused by protein kinase Cγ gene (PRKCG) mutations, the incidence of which is 1%–4% of all autosomal dominant cerebellar ataxias." (PMID 33478986, 2021). "Mutations in the protein kinase Cγ gene (PRKCG) cause spinocerebellar ataxia type 14 (SCA14)." (PMID 32860158, 2020). "Spinocerebellar ataxia type 14 is caused by mutation to of the PRKCG gene, which encodes the PKCγ isoform of the PKC subfamily (PKCγ) and is activated by binding with the secondary messenger DAG, in the presence of phosphatidylserine." (PMID 32765211, 2020). "Spinocerebellar ataxia type 14 (SCA14) is caused by missense mutations or deletions in the PRKCG gene, coding for protein kinase C gamma (PKCγ)." (PMID 28738819, 2017). "Spinocerebellar ataxia type 14 (SCA14) is an autosomal dominant neurodegenerative disorder that is clinically characterized by symptoms of cerebellar dysfunction and is caused by missense or deletion mutations in the PRKCG gene encoding protein kinase Cγ (γPKC)." (PMID 22363588, 2012). "The investigation included patients with spinocerebellar ataxia type 14, which has been more recently termed SCA-PRKCG (protein kinase C gamma)." (PMID 38894268, 2024). "Spinocerebellar ataxia type 14 (SCA14), characterized by slowly progressive cerebellar dysfunction, dysarthria and abnormal eye movements, is caused by almost 40 different mutations in PRKCG gene, encoding the protein kinase C gamma (PKCγ)." (PMID 31892274, 2019).
colon carcinoma (15 papers, 2014 to 2025). "The role of PRKCG in osteosarcoma 18, colon cancer 19, gliomas 20, breast cancer 21, ovarian cancer 22 and hepatocellular carcinoma 23, 24 is established." (PMID 39668814, 2024). "The overexpressed PRKCG gene plays a role in the tumorigenesis of colon cancer, especially in the process of cancer migration." (PMID 32986378, 2020). "In addition, a previous study revealed that PRKCG was upregulated in colon cancer and promoted the migration of colon cancer cells." (PMID 40836964, 2025). "A past study compares the expression of non-phosphorylated and Thr514-phosphorylated form of PRKCG in colon cancer cells." (PMID 39668814, 2024).
glioma (8 papers, 2020 to 2025). A benign or malignant brain and spinal cord tumor that arises from glial cells (astrocytes, oligodendrocytes, ependymal cells). "Through comprehensive molecular profiling across different datasets, we revealed that PRKCG (Protein Kinase C Gamma), a brain-specific gene detectable in cerebrospinal fluid, is closely associated with glioma." (PMID 32539851, 2020). "We revealed that PRKCG, a gene specifically expressed in brain and detectable in cerebrospinal fluid (CSF), is closely associated with glioma, indicative of a potential biomarker for glioma diagnosis, prognosis and treatment prediction." (PMID 32539851, 2020). "PRKCG bears the great potential for glioma diagnosis, prognosis and therapy, and PRKCG-like genes may represent a set of important genes associated with different molecular mechanisms in glioma tumorigenesis." (PMID 32539851, 2020). "MCOLN2, TRPV4, and ITPR2 were significantly highly expressed in glioma tissues, and the three most significantly down-regulated genes (PRKCG, CAMK2A, and HTR2A) had lower expression in tumor tissues." (PMID 41331166, 2025). "In gliomas, PRKCG expression and methylation patterns correlate with tumor progression, with glioblastomas exhibiting the lowest expression and highest methylation." (PMID 40430278, 2025). "PRKCG expression/methylation change from high to low is indicative of glioma progression from low-grade to high-grade and high RNA expression is suggestive of good survival." (PMID 32539851, 2020). "Through comprehensive molecular profiling, we identified that PRKCG, a brain-specific gene detectable in CSF, is a potential biomarker for glioma diagnosis, prognosis and treatment prediction." (PMID 32539851, 2020). "In harmony with classical biomarkers, PRKCG as well as PRKCG-like genes may play important and heterogeneous roles in glioma tumorigenesis." (PMID 32539851, 2020). "Given that PRKCG and its phosphosites were downregulated in the BrM/BrM‐NAT group, the ultra‐high phosphorylation level of PRKCG at S330 in gliomas is particularly noteworthy." (PMID 39716938, 2025). "In the glioma pathway (hsa05214), included in CDK4 (Cyclin Dependent Kinase 4), PRKCG (Protein Kinase C Gamma) and EGFR." (PMID 32696617, 2020).
Stroke (7 papers, 2016 to 2025). Sudden impairment of blood flow to a part of the brain due to occlusion or rupture of an artery to the brain. "The two stroke groups also showed a comparable loss of corticospinal tract axons as assessed in the upper cervical dorsal columns using protein kinase C gamma (PKCγ) immunofluorescence." (PMID 26614754, 2016). "Eight common genes were found across all three compounds and stroke: MAPK1, PRKCB, PRKCG, HDAC1, HTR1A, HTR2A, HTR2C, and HTR7." (PMID 41011194, 2025).
peripheral nerve injury (6 papers, 2010 to 2024). Injury to a peripheral nerve. "The NI/Sham LPF ratio of two ACC proteins, KPCG (protein kinase C gamma, PKCγ) and CH60 (mitochondrial 60 kDa heat shock protein, HSP60) indicated a significant turnover rate change following peripheral nerve injury (Sham vs. Nerve injury, unpaired t-test, PKCγ, p < 0.01, HSP60, p < 0.05)." (PMID 32051001, 2020).
Cerebellar atrophy (5 papers, 2021 to 2025). Cerebellar atrophy is defined as a cerebellum with initially normal structures, in a posterior fossa with normal size, which displays enlarged fissures (interfolial spaces) in comparison to the foliae secondary to loss of tissue. "This autosomal dominant disease is caused by missense variants in PRKCG, the gene encoding PKCγ, and leads to cerebellar atrophy and loss of motor coordination and function." (PMID 37551632, 2023).
autosomal dominant cerebellar ataxia (4 papers, 2010 to 2021). A clinically and genetically heterogeneous group of neurodegenerative diseases characterized by a slowly progressive ataxia of gait, stance and limbs, dysarthria and/or oculomotor disorder, due to cerebellar degeneration in the absence of coexisting diseases. "Therefore, an autosomal dominant cerebellar ataxia with normal SCA repeats, especially when slow progression and predominantly pure phenotype is predominant, should alert the physician to test for PRKCG mutations." (PMID 29603387, 2018). "We studied a large cohort (n = 194) of mainly pure, autosomal dominant cerebellar ataxia cohort negative for trinucleotide repeats and identified 13 families with disease‐causing mutations in PRKCG with a variable spectrum of disease phenotype and severity." (PMID 29603387, 2018).
Cerebral ischemia (4 papers, 2007 to 2026). Restriction of arterial blood supply to the brain associated with insufficient oxygenation to support the metabolic requirements of the tissue. "MAPK1 and the PKC isoforms PRKCB and PRKCG have been shown to mediate pro-apoptotic responses, oxidative stress, and neuroinflammation following cerebral ischemia." (PMID 41011194, 2025).
ischemic stroke (4 papers, 2020 to 2026). A stroke disorder caused by obstruction of blood flow to the brain, due to thrombotic (local blood clot formation) or embolic (due to a blood clot or other material traveling from another site) event. "In particular, TRPM2-NMDAR coupling is enhanced subsequent to ischemic stroke, resulting in a Protein Kinase C gamma (PKC-γ)-dependent increase in NMDAR expression at the cell surface." (PMID 37631001, 2023).
osteosarcoma (4 papers, 2021 to 2024). A usually aggressive malignant bone-forming mesenchymal neoplasm, predominantly affecting adolescents and young adults. "PRKCG rs454006 was significantly associated with an increased risk of osteosarcoma under the homozygous and the allele models in the main analysis." (PMID 38360742, 2024). "Polymorphism of SNP rs454006 in PRKCG was demonstrated to increase the risk of patients with osteosarcoma." (PMID 34631528, 2021).
Anxiety (3 papers, 2012 to 2024). Intense feelings of nervousness, tension, or panic often arise in response to interpersonal stresses. "In support of PKC overactivity in models of mental illness, a PRKCG KO mouse paradigm displays decreased anxiety." (PMID 40836982, 2024). "However, the precise roles of PRKCG and LRRTM1 in TAO are unknown, and we suspected they may be involved in the mechanisms of the impaired emotional regulation and higher tendency to depression or anxiety occurring in TAO patients." (PMID 36056316, 2022).
breast carcinoma (3 papers, 2021 to 2024). "Studies have found that mutations in the PRKCG gene increase breast cancer susceptibility." (PMID 33968297, 2021). "Furthermore, upregulation of PRKCG promoted cell proliferation and glycolytic metabolism of breast cancer cells." (PMID 39039568, 2024). "However, research on PRKCG gene in the context of breast cancer is scarce." (PMID 39039568, 2024).
Dystonia (3 papers, 2018 to 2025). An abnormally increased muscular tone that causes fixed abnormal postures. "Meanwhile, cases classified as “quite inconsistent” were mostly focal (n = 15) or segmental/multifocal (n = 8) dystonia and involved variants in genes typically associated with other disorders where dystonia is rarely reported, such as C19orf12, GRN, KIF1A, and PRKCG." (PMID 40533913, 2025).